IL6 (interleukin 6)
Diseases named in the same sentence as IL6 in open-access papers (continued):
Sharing a sentence is not in itself a finding about the gene and the disease.
cancer (continued). "Particularly, we identified three sesquiterpene lactones, costunolide, dehydrocostuslactone, and cynaropicrin, able to inhibit IL-6-induced as well as constitutive activation of STAT3 in different cancer cell lines." (PMID 31781335, 2019). "IL-6 is highly up-regulated in many cancers and is considered as a crucial cytokine during tumorigenesis." (PMID 31396215, 2019). "Conversely, IL-6 has been correlated with tumorigenesis, muscle wasting and decreased survival time in patients with cancer cachexia." (PMID 31842339, 2019). "When we performed qPCR in different human GC cell lines and fibroblasts, interestingly, sIL6R, mIL6, and gp130 mRNAs were expressed in cancer cells and paired fibroblasts, whereas IL6 mRNA was expressed almost exclusively in fibroblasts." (PMID 30927911, 2019). "In conclusion, our results demonstrate that LPE reduces the invasiveness of gastric MKN-28 and AGS cancer cells through the reduction of IL-6-induced MMP-9/2 up-regulation." (PMID 31817563, 2019). "We have previously shown that icaritin exhibits anti-proliferative activities both in cancer cells and in cancer-stem cells through the IL-6/Jak2/Stat3 pathway both in vitro and in vivo." (PMID 30922248, 2019). "IL-6 promotes tumorigenesis by altering DNA methylation in cancer cells, by inducing both the expression of DNMT1 and its nuclear translocation through phosphorylation of its NLS via PI-3K/AKT signaling." (PMID 31557902, 2019). "Given the robust role of IL-6 as a pro-tumorigenic cytokine in several types of cancer, we therefore assayed alterations in their levels." (PMID 31142771, 2019). "Overexpression of IL-6 has been found in most cancer types, particularly NSCLC, and has been shown to have an inverse correlation with patient prognosis and higher resistance to chemotherapy." (PMID 32039025, 2019). "bCAFs favor MCL-1 expression and apoptotic resistance in luminal cancer cells in a IL-6 dependent manner while their own, robust, survival also relies on MCL-1." (PMID 30631150, 2019). "Following 24 h of treatment, A009 was able to reduce IL-6 and STAT3 phosphorylation (Ser727) in DU-145, showing a potential cancer-preventive role by blocking IL-6/STAT3 signaling in vitro." (PMID 30646518, 2019). "Data from previous studies have confirmed that elevated IL-6 levels are observed in patients with a variety of cancers." (PMID 31412593, 2019). "IL-1α and IL-1β are amongst the most prominent and potent inflammatory cytokines, together with TGFβ, TNFα, and IL-6, in the TME, and are implicated in cancer-related inflammation." (PMID 31557902, 2019). "In support of the notion that inflammation-activated or dysfunctional vasculature occurs in cancer progression, circulating levels IL-6 and TNF-α have been correlated with the risk of developing cancer, and with increased cancer deaths among older adults." (PMID 31656195, 2019). "Proteomic analysis of the content of these exosomes identified several established cancer- related proteins (i.e., IL-6, IL-8, ICAM-1, CCl2, and OSM)." (PMID 31803630, 2019). "Consistent with its function in cancer progression, IL-6 was also upregulated in WHF from larger late-stage tumors." (PMID 30791501, 2019). "Among these cytokines, IL-6 is an important mediator which can be secreted by immune, fibroblasts and cancer cells." (PMID 30989585, 2019). "Serum IL-6 level-based cancer prognosis in the Multi-Ethnic Cohort Study revealed association with significantly poor survival in AAs (Hazard ratio: 2.71) compared to CAs (Hazard ratio: 1.71)." (PMID 31769418, 2019). "The suppression of bcl-2 and IL-6 by either pre- and post-application of inhibitor is especially important because of bcl-2 role in anti-apoptosis and IL-6 role as a cancer-related cytokine." (PMID 31164956, 2019).
cancer (continued). "The IL6/STAT3 signaling pathway has been suggested as an attractive target for the discovery of novel cancer therapeutics." (PMID 30674340, 2019). "We found that LDOC1 deficiency led to reinforcing a reciprocal loop of IL-6/JAK2/STAT3, through which LDOC1 mediates the cancer progression." (PMID 30634502, 2019). "The combination of MCT-1 and IL-6/IL-6R pathway cooperatively enhanced cancer stemness and the oncogenic effects." (PMID 30885232, 2019). "Impressively, the SCNE dramatically depressed key circulating pro-cancer inflammatory cytokines (IFNγ, TNFα, IL-6, IL-1α, and IL-1β) in all of the xenograft and 4NQO-1 mouse models tested." (PMID 31572681, 2019). "Firstly, the addition of recombinant IL-6 (rIL-6) to cancer cells decreased their response to ABT-737." (PMID 30631150, 2019). "The increased proinflammatory cytokines, including IL-6 and IL-8 levels, were a part of explanations for multidrug and apoptosis resistance in cancers." (PMID 31456937, 2019). "IL-6 gene transcription itself is directly modulated by histone acetylation and methylation in macrophages and in cancer cell lines." (PMID 31114509, 2019). "The inflammatory cytokine IL-6 is known to be involved in the pathogenesis and progression of various cancers." (PMID 31771617, 2019). "Recent studies reported that up-regulation of IL-6 level leads to cancer cells resistance to chemotherapeutic drugs." (PMID 30947706, 2019). "We also found that fibroblasts isolated from the peripheral tissue of the cancers showed comparable levels of IL-6." (PMID 31795965, 2019). "Many recent studies showed that IL-6 plays a pivotal role in cancer development, chemoresistance, and cancer stem cell maintenance." (PMID 30755239, 2019). "AKR1C1, STATs, and cytokine IL-6 potentially form a positive feedback loop in cancer to enhance cisplatin-resistance." (PMID 31182137, 2019). "In CRC, MSCs secrete prostaglandin E2 (PGE-2) in response to IL-1 released by carcinoma cells, which act in an autocrine fashion to induce the expression of IL-6, IL-8 and CXCL-1, which together induce the formation of CSCs." (PMID 31417869, 2019). "IL-6 and leptin were identified as important factors involved in cancer progression in a study examining the over-production of inflammatory cytokines due to chronic low-grade inflammation." (PMID 30563531, 2018). "For example, the IL-6 inhibitor, tocilizumab, has shown promising results in the treatment of cancer cachexia." (PMID 30081609, 2018). "Serum levels of IL‐6 were elevated in all cancer‐bearing mice, though there was a trend toward decreased levels in AICAR (non‐significant) and metformin (significant)‐treated mice." (PMID 29844217, 2018). "Several studies have established a strong association between tumors and chronic inflammation, demonstrating the overexpression of several inflammatory cytokines, such as IL-1, IL-6, IL-4 or IL-8 in tumor tissue or serum of cancer patients." (PMID 29351242, 2018). "Human Cytokine Array analysis showed that cancer patients have a significant increase in saliva expression of pro-inflammatory markers IL-1a, IL-1b, IL-6, IL-8, and TNFα compared to controls." (PMID 30018735, 2018). "Increased levels of serum IL-6 and IL-8 are commonly observed in cancer patients, and are positively correlated with the number of infiltrating MDSCs in breast cancer." (PMID 29988030, 2018). "A previous population-based cancer study also showed that pro-inflammatory cytokines, such as TNFa, IL-6, and VEGF were elevated and promoted the angiogenesis/metastasis process." (PMID 30485279, 2018). "More recently, IL-6 has emerged as the key determinant of muscle mass wasting in advanced cancer patients." (PMID 30294279, 2018).
cancer (continued). "For example, in PDAC a specific subset of CAFs expressing high levels of αSMA but low levels of IL-6 was found in the fibrotic area juxtaposed to cancer cells and was called the myofibroblast CAF subset (myCAFs)." (PMID 30356656, 2018). "Evidence from other systems demonstrates that the inflammatory cytokines IL-6 and IL-8 promote cancer progression." (PMID 30119678, 2018). "Certain types of cancer can promote the up-regulation of pro-inflammatory cytokines including interleukin-6 (IL-6), tumor necrosis factor-α (TNFα), and interferon-γ, many of which are anorexigenic and/or proteolytic." (PMID 30460194, 2018). "Tumor necrosis factor alpha (TNF-α) and IL-6 are two of the best-studied pro-inflammatory and pro-tumorigenic cytokines, the expression of which are elevated in many different cancers." (PMID 30563089, 2018). "The pro-tumorigenic nature of IL-6 has been studied in various cancers including breast, pancreas, renal, and prostate tumors." (PMID 29662489, 2018). "As IL-6 appears to be a valid predictor in cancer prognosis, it would be useful to further examine the effects of cumulative past exposure to various health behaviors on IL-6 serum levels." (PMID 29951282, 2018). "On the other hand, use of monoclonal antibodies against pro-inflammatory cytokines (TNF-alpha and IL-6) in different cancers led to sporadic disease stabilization, thus suggesting the poor efficiency of such a therapeutic strategy." (PMID 29558948, 2018). "Interleukin 6 (IL-6) is a cytokine secreted by M2 macrophages that promotes cancer cell metastasis by activating signal transducer and activator of transcription 3 (STAT-3) and repressing E-cadherin expression." (PMID 30266897, 2018). "Much effort has been put forth to study the mechanistic role of IL‐6 in PCa, supporting that IL‐6 is a key cancer‐promoting factor and rational therapeutic target." (PMID 29741809, 2018). "In this study, we found that USP24 is not only upregulated in malignant cancer cells but also in M2 macrophages and participates in cancer metastasis by positively regulating IL-6 expression through multiple genetic and epigenetic mechanisms." (PMID 30266897, 2018). "In our patient, the serum level of IL-6 was discreetly high, which is frequently observed in cancer patients." (PMID 30587227, 2018). "IL-6, IL-8, CXCL1, GM-CSF, and TGFβ2 are recognized pro-tumorigenic factors associated with cancer progression." (PMID 30111846, 2018). "In cancer cachectic mice, we found inhibition of IL-6 significantly preserved the weights of inguinal and epididymal WAT." (PMID 29338749, 2018). "Several studies reported that the synthesis of proinflammatory cytokines, notably IL-6 and IL-8, promotes activation of pro-survival pathways in cancer cells." (PMID 30310111, 2018). "Another aspect of skeletal muscle metabolism, regulated by IL6/STAT3 pathway in cancer cachexia, is the process of muscle repair via satellite cells recruitment." (PMID 30072615, 2018). "Blockade of the IL-6 signaling pathway has been regarded as a target for the therapy in variety of cancers." (PMID 30333255, 2018). "A recent report by Nan and colleagues, however, found that IRF9 contributes to STAT3 activation by upregulating IL6 expression in cancer cells." (PMID 30515152, 2018). "One of the most surprising outcomes is the verification that objective responses to sunitinib are accompanied by significantly lower or even undetectable levels of the proangiogenic cytokines IL-8 and IL-6, in line with data obtained in other cancers." (PMID 30651923, 2018). "Our findings showed that UBE2D1 played a crucial role in HCC progression, and suggested a novel pattern of continuous IL-6 to promote cancers by inducing the genomic alterations of specific oncogenes." (PMID 30482241, 2018).
cancer (continued). "On the other hand, ectopic expression of ATR suppressed the expression/secretion of several cancer-promoting proteins such as IL-6, TGF-β1 and SDF-1, and inhibited the migration and invasion capacities of breast myofibroblast cells." (PMID 30410668, 2018). "The IL-6/STAT3 paracrine signaling pathway from TAMs also triggers the proliferation of cancer progenitor cells to facilitate hepatocarcinogenesis." (PMID 30104473, 2018). "Previous studies examining IL-6 regulation indicated that the level of DNA methylation in the IL-6 promoter regulates transcriptional activity in cancer cells." (PMID 30266897, 2018). "In this study, different mechanistic details regarding USP24-mediated IL-6 expression were observed in M2 macrophages and cancer cells." (PMID 30266897, 2018). "Cancer cell adhesion to IL-6/IL-10 stimulated blood and lymphatic endothelial cells (EC) was investigated." (PMID 29256156, 2018). "Interleukin 6 (IL-6) up regulates myeloid cell leukemia-1 (Mcl-1), a protein that is important in the anti-apoptotic factors in the development of cancer in the biliary epithelial cells." (PMID 30613437, 2018). "Clinical analyses showed positive significant association between serum IL-6 and free fatty acid (FFA) both in early- and late-stage cancer cachexia." (PMID 29338749, 2018). "The active status of myofibroblasts is sustained even in absence of the activating signal, due mainly to the activation of the IL-6/STAT3/NF-κB positive feedback loop that links inflammation to cancer." (PMID 29707149, 2018). "In clinical studies, the levels of IL-6 in plasma of cancer patients were positively correlated with the progression of cancer symptoms." (PMID 29794990, 2018). "Particularly, CRP, IL-6 and TNF-α, in particular, have been reported to be associated with a variety of cancers." (PMID 29844870, 2018). "For example, Ara and colleagues demonstrated that in neuroblastoma the bone marrow microenvironment is a source of IL-6 and sIL-6R, thereby allowing cancer cells to escape the cytotoxic effects of multiple chemotherapeutics." (PMID 29946544, 2018). "The case of IL-6 blockade in CRS illustrates the potential of targeted immunological interventions for the management of toxicities of cancer immunotherapy." (PMID 29907163, 2018). "IL6 stimulates survival, proliferation, and progression to cancer of intestinal epithelial cells via activation of signal transducers and activators of transcription 3 (STAT3), eventually inducing the expression of SCOS3." (PMID 30662576, 2018). "It has previously been shown that the subcutaneous injection of C26‐adenocarcinoma cells into the flank of these mice leads to the development of cancer cachexia‐like symptoms due to the production of pro‐inflammatory cytokine, such as IL‐6." (PMID 29844217, 2018). "In vitro treatment with Hst on various cancer cell lines showed significant down-regulation of IL-6 induced p-STAT3 (Tyr705) expression." (PMID 29963254, 2018). "In this context, the finding that treatment with anti-IL6 mAb in patients with advanced cancer at different sites is able to significantly increase Hb levels is of high relevance." (PMID 30294279, 2018). "Our work shows that IL-1β derived from inflammatory UC-MSCs induces the production of downstream cytokines CCL2, CXCL1, IL-6, and IL-8 in an autocrine manner, which promotes stem cell-like characteristics of cocultured cancer cells." (PMID 29670904, 2018). "As shown in endometrial cancer, IL-6 secreted by CAFs stimulates cancer cell proliferation via the STAT3/c-MYC signaling pathway." (PMID 29883428, 2018). "The function of cancer stem cells is modulated by many signaling pathways, including IL-6/STAT3, hedgehog, WNT, and Notch." (PMID 30312311, 2018). "IL-6 is widely recognized for its crucial role in cancer promoting inflammation, which relies on STAT3 as both survival and tolerogenic signaling." (PMID 29541413, 2018).
cancer (continued). "Several of the studies investigated in this review assessed the correlation between serum IL-6 and CRP levels in cancer patients, and the majority found a significant correlation between IL-6 and CRP." (PMID 30038723, 2018). "Our data demonstrate that NF-κB inhibition can block the acidic bile-induced overexpression of TNF-α, NF-κB transcriptional factor RELA(p65), and cancer related cytokines, IL-1β and IL-6." (PMID 29464041, 2018). "Some of the key inflammatory mediators are TGF-β, TNF-α and interleukins 6 and 10 (IL-6 and IL-10), and these factors have been shown to initiate and promote cancer development." (PMID 30487436, 2018). "Increasing evidence demonstrates that the JAK/STAT3, PI3K/AKT and MEK/ERK pathways are frequently activated by adipokines, such as IL-6 and leptin and that these pathways are often altered in several types of cancer." (PMID 30563531, 2018). "The results of this review show that açaí acts in the inflammatory processes involved in induced-cancer in animals by decreasing the levels of IL-1β, IL-5, IL-6, IL-8, COX-2, TNF-α and MPO and increasing the levels of IFN-γ." (PMID 29966007, 2018). "Future studies should therefor differentiate between early and late cancer stages when investigating the use of IL-6 as a prognostic biomarker." (PMID 30038723, 2018). "Meanwhile, we found that suppression of IL-6 induced apoptosis and reduced the cell survival or tumorigenicity of the cancer cells." (PMID 29693005, 2018). "One population secretes abundant proinflammatory IL-6 as a result of paracrine interactions with the cancer cells whereas the second population of fibroblasts secretes a highly desmoplastic stroma following direct juxtacrine interactions with the cancer cells." (PMID 29883385, 2018). "Inflammation plays an important role in the development and growth of cancer, which has led to a growing interest in the pro-inflammatory cytokine interleukin 6 (IL-6)." (PMID 30038723, 2018). "IL-8 (and IL-6) can activate cancer aggressiveness by the induction of cancer metastasis and PTX resistance." (PMID 29486738, 2018). "Here, we will focus on the immunosuppressive effect, more frequently described in cancer, while we will refer to the pro-inflammatory, immune-activating effect of IL-6 in the chapter on cancer cell senescence." (PMID 30154786, 2018). "Since autophagy inhibition has been shown to decrease IL-6 and 8 secretion, inhibition of autophagy during cancer therapy would decrease their secretion in cancer cells." (PMID 30622432, 2018). "Next, we evaluated the impact of cancer-derived exosomes on the IL-6/STAT3 signaling pathway in macrophages." (PMID 29867925, 2018). "In our study, proliferation of the cancer cells was substantially suppressed in a time-dependent pattern when gemcitabine and shRNA targeting IL-6 were used together." (PMID 29693005, 2018). "Inflammation too is a key driver in cancer cachexia possibly through increased expression of pro-inflammatory cytokines like IL-6 and TNF-a and induction of acute phase protein response, a key marker of systemic inflammation." (PMID 30482179, 2018). "In the same way, in the setting of cancer cachexia, IL-6 and TNF-α are considered to be critical drivers of lipolysis and fat depletion, with recent evidence of AT production of these cytokines." (PMID 30094378, 2018). "This study shows that USP24 mediates p300, NF-κB, DNMT1, and β-TrCP to regulate IL-6 expression, thus affecting cancer metastasis." (PMID 30266897, 2018). "Elevated IL-6 production and NF-κB activation contribute to cancer progression and chemo-resistance." (PMID 30405034, 2018). "As the result, the most efficient restoration of IL-6 levels by IFBOs provided evidence of their cellular functioning through the curtailment of IL-6 gene over-expression at cancer sites." (PMID 29651140, 2018). "This shows that let-7b negatively controls 2 major imflammatory/cancer-related cytokines IL-6 and IL-8." (PMID 29707149, 2018).